CCR5AS (CCR5 antisense RNA)
Gene: Long non-coding RNA gene on chromosome 3 (46,363,984 to 46,407,184, reverse strand). Ensembl gene ENSG00000223552.
Diseases named in the same sentence as CCR5AS in open-access papers:
CCR5AS is named in the same sentence as 6 diseases in open-access papers, as found by Europe PMC text mining. Sharing a sentence is not in itself a finding about the gene and the disease. The quoted sentences say what the papers report.
COVID-19 (3 papers, 2021 to 2022). A disease caused by infection with severe acute respiratory syndrome coronavirus 2. "Six genes (namely, SLC20A6, CCR9, CXCR6, CCR2, CCR5, and CCR5AS) were significant from the MR-JTI analysis after Bonferroni correction, indicating causal support for these genes on COVID-19 hospitalization." (PMID 35318325, 2022). "A summary data-based Mendelian randomization (SMR) analysis and a transcriptome-wide association study (TWAS) were performed for the severe COVID-19 dataset, and seven novel genes for severe COVID-19 were identified, including CCR5, CCR5AS, IL10RB, TAC4, RMI1, and TNFSF15." (PMID 36483456, 2022).
dementia (1 paper, 2024). Loss of intellectual abilities interfering with an individual's social and occupational functions. "These nominated causal genetic variants are located on the IL34, CCR5AS genes and the HLA intergenic region, all of which are involved in neuroinflammatory responses relevant to dementia." (PMID 39649611, 2024).
melanoma (1 paper, 2023). A malignant, usually aggressive tumor composed of atypical, neoplastic melanocytes. "Previous bioinformatics investigations have demonstrated the prognostic value of CCR5AS and LINC01749 in melanoma and ESCC, respectively." (PMID 37686677, 2023).
virus infection (1 paper, 2020). "lncRNA NEAT, 7SL, NRAV, lnc-ISG20, and CCR5AS have been reported to regulate the innate immune responses to virus infection." (PMID 32153544, 2020).
cancer (2 papers, 2020 to 2023). A tumor composed of atypical neoplastic, often pleomorphic cells that invade other tissues. "Several of these lncRNAs in the risk model have been reported to play significant roles in different cancers, such as CCR5AS, LINC01749, TMEM220-AS1, KCNMA1-AS1, SNHG1, and LINC01672." (PMID 37686677, 2023).
infection (1 paper, 2025). The state of being infected such as from the introduction of a foreign agent such as serum, vaccine, antigenic substance or organism. "CHROMR expression was similarly upregulated by IAV and SARS-CoV-2, infection, while other lncRNAs that were tested were preferably enhanced by either IAV (BISPR, NRIR, CCR5AS) or SARS-CoV-2 (LUCAT1) infection." (PMID 40559622, 2025).